GFAP (glial fibrillary acidic protein)
Diseases named in the same sentence as GFAP in open-access papers (continued):
Sharing a sentence is not in itself a finding about the gene and the disease.
tumor (continued). "Survivin and GFAP were evaluated both independently and together as possible tumor markers on CD9+ exosomes." (PMID 29383115, 2017). "H&E staining and GFAP Immunohistochemistry experiments revealed the xenograft tumor in mice origin of implanted U251 and U251SLC cells." (PMID 29246166, 2017). "In recurrent tumor #1614, cells in the tumor core displayed strong (+++) positivity of GFAP and VIM while a small piece of normal tissue demonstrated significant numbers of VIM+/GFAP− tumor cells." (PMID 29152094, 2017). "Ki67 staining indicated strong proliferation, and uniform expression of GFAP and Olig2 confirmed the glial nature of all tumours." (PMID 28695888, 2017). "The GFAP/Nestin double positive phenotype was also found, at a reasonable frequency (1.2 ± 0.3%; n = 14 tumor samples), in the original tumor tissue." (PMID 29163787, 2017). "Using our new PDOX model, we were able to detect the cellular drivers of tumor progression, i.e. GFAP−/VIM+ tumor cells." (PMID 29152094, 2017). "These tumors displayed well-demarcated smooth borders with adjacent tissues and reactive gliosis confirmed with GFAP staining in adjacent tissues to the tumor." (PMID 28824165, 2017). "When the tumor cells derived from these tumor spheres were differentiated, GFAP positive astrocytes and Tuj-1 positive neurons were detected, although the morphology of these cells still remained immature." (PMID 26908439, 2016). "He presented clinical data showing, that RTK-AXL is mainly expressed in pseudo-palisades and GFAP positive tumor cells, whereas the specific ligand of RTK-AXL Gas6 is expressed in hypoxic border zone but not in pseudo-palisades." (PMID 26848524, 2016). "Immunohistochemistry demonstrates tumor cells were positive for GFAP, OLIG2, SOX2, IDH1(R132H) and a MIB1 proliferation index of >30 %." (PMID 26817999, 2016). "Tumor cells and their processes react with GFAP and collagen fibers stain strongly blue with Masson’s trichrome." (PMID 27568373, 2016). "The earliest method used to find CTCs was based on the detection of tumor cell surface specific markers such as EpCAM, cytokeratins (CKs) and glial fibrillary acidic protein (GFAP) etc.." (PMID 27517490, 2016). "Immunohistochemical analysis for GFAP confirmed tumor formation originated in the glia, and Ki67 detection revealed a high number of cycling cells in the tumor tissue." (PMID 27244897, 2016). "In the tumor area, even if GFAP labeling was weaker and diffused, cells exhibiting Cx43 nuclear staining were not GFAP positive." (PMID 27306693, 2016). "As determined by immunohistochemical analysis, the tumor samples showed various range of reactivity to GFAP, EGFR and the proliferation marker ki67." (PMID 26755664, 2016). "In the differentiation assay, tumor spheres were differentiated and display immunoreactivity for astrocyte’s maker glial fibrillary acidic protein (GFAP, red) and neuron marker β-tubulin-III (green)." (PMID 27801803, 2016). "Immunohistochemical staining result showed that positive GFAP staining was observed in the tumor area, confirming that the tumor tissue was astrocytic origin (arrow)." (PMID 27852319, 2016). "The merged image shows that the IL-8 expression is mainly present in GFAP positive tumor cells, preferentially in the perinecrotic region (Fig. 2b8)." (PMID 27076368, 2016). "Immunohistochemistry was performed, which showed that the tumour cells were diffusely positive for S100 and glial fibrillary acidic protein (GFAP)." (PMID 27239359, 2016). "The tumor was immunonegative for GFAP, creatine kinase, Syn and B-cell lymphoma 2; however, it was immunopositive for vimentin, EMA, S-100 and TTF-1." (PMID 25777996, 2015).
tumor (continued). "Histopathological examination revealed an extensively hyalinized tumor with sparse collections of cells that were immunopositive for both cytokeratin and GFAP, and immunonegative for EMA and progesterone receptor." (PMID 26155457, 2015). "Nestin was expressed at high levels by virtually all tumor cells while ~30–40% of the cells expressed GFAP and βIII tubulin was weakly present in ~5–8% of the cells." (PMID 25919028, 2015). "The bipolar tumor cells are generally strongly GFAP immunoreactive, while the protoplasmic astrocyte-like tumor cells are less so." (PMID 25792358, 2015). "Tumor cells were highly positive for glial fibrillary acidic protein (GFAP), and the Ki67 index was approximately 10%." (PMID 25885250, 2015). "The positive correlation observed between miR21 and the expression of tumor GFAP supports the role of astrocytes as targets of regulation and as a source of miR21." (PMID 25986346, 2015). "Univariate analysis showed that high tumor stage, positive glial fibrillary acidic protein (GFAP) expression, radiochemotherapy, total resection, and high UBE3C expression were predictors for OS and PFS." (PMID 26067607, 2015). "Co-staining for GFAP / CD105 was more frequent than co-staining for GFAP / CD31 with CD105 positive TDEC observed in the vicinity of peri-necrotic areas within the tumor." (PMID 26203665, 2015). "Immunohistochemistry showed that the tumor cells were positive to glial fibrillary acidic protein (GFAP) and S-100 protein." (PMID 25957575, 2015). "We investigated this question using double-labeling of all of the tumor samples previously used for double-labeling with Sox2 and tumor-specific antibodies with IHC for Sox2 and GFAP." (PMID 25713758, 2015). "In this case, the use of GFAP for CTC identification was supported by its absence in control participants, and the presence of EGFR amplifications in the tumor cells isolated using GFAP." (PMID 26322014, 2015). "There was a dramatic increase in GFAP and βIII tubulin expression in tumor cells (40–50%), most of which displayed an elongated morphology with a concomitant reduction in Ki67 expression (4–5%)." (PMID 25919028, 2015). "Tumor cells had significant pleomorphism and atypia accompanying GFAP expression and 5 % index of Ki-67 labeling." (PMID 25957575, 2015). "In this case, the use of a molecular biomarker for CTC isolation was supported by its absence in control participants, and the presence of EGFR amplifications in the tumor cells isolated using GFAP." (PMID 26636033, 2015). "Primary tumours expressing the astrocyte marker GFAP maintained the expression in corresponding monolayer and sphere cultures, whereas GFAP negative primary tumours remained negative in cell cultures." (PMID 26183281, 2015). "By immunohistochemistry, the tumor cells showed nuclear labeling for S100, with diffuse background staining for both S100 and glial fibrillary acidic protein (GFAP)." (PMID 25755903, 2015). "The center of the implant was populated by clusters of tumor cells which strongly expressed nestin, a neuronal stem cell marker and, to a lesser degree, GFAP, an astrocyte differentiation marker." (PMID 25919028, 2015). "Sox-2, Olig-2 and GFAP were present at high levels in proliferative cells and expressed in the invasive part of the tumor, and T121 staining confirmed suppression of RB (Sox-2, Sox-2/I, Olig-2, Olig-2/I, T121, T121/I and GFAP, GFAP/I)." (PMID 25431423, 2015). "In our study, both of the tumor models by TJ905 cells and stem cells highly expressed GFAP, indicating that the tumor originated from astrocytes or differentiated into mature cells." (PMID 26136642, 2015). "SHG139 in the 20th and 60th generations had the same molecular markers and cell morphology: GFAP, S-100 and Vimentin were expressed, and tumor cells were diploid or polyploid." (PMID 25879429, 2015).
tumor (continued). "Iba-1+ microglial cells were distributed homogenously throughout the tumor (center and rim), whereas GFAP+ astrocytes were located mainly at the periphery of the tumors." (PMID 26149494, 2015). "Immunohistochemical analysis of C57BL/6 mouse brains 1 day post intratumoral infection with LIVP 1.1.1 or PBS as control revealed a strong infiltration of the tumor with microglia (Iba-1+) and astrocytes (GFAP+) at both treatment conditions." (PMID 26149494, 2015). "On immunohistochemical staining, it was found that the tumor was positive for S-100, cytokeratin and glial fibrillary acidic protein(GFAP)." (PMID 26161225, 2015). "The tumor was immunonegative for GFAP and Syn, whilst it was immunopositive for vimentin, EMA, S-100 and TTF-1." (PMID 25777996, 2015). "In peritumoral cortex and within the tumor, miR155 was expressed in both neurons and glial cells (NeuN- and GFAP-positive cells); we also observed expression of miR155 in blood vessels (peritumoral cortex and tumor)." (PMID 25986346, 2015). "Immunohistochemical staining showed that the tumor cells were synaptophysin- and NeuN- positive but GFAP- and CK-negative." (PMID 26376790, 2015). "A little expression of CD133 was detected in xenograft tumor (D3), GFAP and S-100 were detected (D4, D6)." (PMID 25879429, 2015). "Immunohistochemistry stain was positive for S-100 and patchy for GFAP in tumor cells and for SMA around the tubule-glandular and tumor cell aggregates and suggested PA of the breast." (PMID 24899901, 2014). "The flow cytometry analyses showed 92.1% cells expressing GFAP, a tumor glial marker, of which 52.5% double stained for CD133 and 71% cells expressing Nestin, an immature neural stem cell marker, of which 44.8% double stained for CD133." (PMID 24432012, 2014). "Microscopically, there was an infiltrated lymph node along one edge, and the mass consisted of sheets of poorly-differentiated metastatic tumor cells positive for GFAP and rarely for synaptophysin." (PMID 25563358, 2014). "Second opinions on the pathologic diagnosis with additional immunohistochemical staining revealed that all of the tumor cells were positive for glial fibrillary acidic protein (GFAP)." (PMID 25563358, 2014). "The tumor cells were positive for tumor cell glial fibrillary acidic protein (GFAP), S-100 protein, vimentin, human leukocyte differentiation antigen 34 (CD34), epithelial membrane antigen (EMA), cluster of differentiation 99 (CD99) and D2-40." (PMID 24348765, 2014). "Immunohistochemical study revealed positive staining of the tumor cells for glial fibrillary acidic protein (GFAP), epithelial membrane antigen (EMA), S-100 protein, and vimentin." (PMID 23546851, 2014). "The statistical analysis of GFAP-IR intensity showed a gradual increase of GFAP expression in 21 days after tumor cell inoculation." (PMID 24580964, 2014). "Cytokines play a major role in this process, along with other proteins including vascular endothelial growth factor (VEGF), matrix metallopreoteinases (MMPs) and glial fibrillary acidic protein (GFAP) that promote angiogenesis and tumor growth." (PMID 24997057, 2014). "Immunohistochemistry has shown the tumor cells to be positive for GFAP, EMA, monoclonal antibody of cell proliferation-associated nuclear antigen (MIB-1) and cell cycle-associated nuclear antigen Ki-67." (PMID 24348765, 2014). "A right iliac crest bone marrow biopsy was performed, and it showed 60% infiltration with GFAP-positive and nestin-positive tumor cells, while synaptophysin was focally positive." (PMID 25563358, 2014). "But, the other part of the tumor showed a large nuclear size and 11.4% of this part appeared to be GFAP-positive by immunohistochemistry." (PMID 24989033, 2014). "The tumor showed positive staining with antibodies to neuron specific enolase, vimentin, S-100, and GFAP." (PMID 25144312, 2014). "Tumor differentiation was assessed by histologic characters and the status of glial fibrillary acidic protein (GFAP)." (PMID 24741354, 2014).
tumor (continued). "The tumor cells showed marked positivity for glial fibrillary acidic protein (GFAP) and S-100 proteins, whereas the cells were negative for epithelial membrane antigen (EMA), cytokeratins (CK) and epidermal growth factor receptor (EGFR)." (PMID 24137352, 2013). "Following transfection with Ad-GFAP-hNIS, the protein level of the hNIS gene was analyzed by western blotting in the U251 and U87 tumor cells and MRC-5 normal cells." (PMID 23420532, 2013). "In the present case, tumor cells showed marked cytoplasmic staining for GFAP and S-100 protein, whereas immunoreactivity for CK, EMA, chromogranin, EGFR and synaptophysin were all negative." (PMID 24137352, 2013). "131I therapy retarded Ad-GFAP-hNIS transfected-tumor growth following injection with 131I in U87 xenograft-bearing nude mice." (PMID 23420532, 2013). "Expression of GFAP positive HSCs cell lines LX-2 was significantly decreased after stimulation with tumor conditioned medium." (PMID 23601182, 2013). "In this system, omission of Ras, that is combined expression of c-Myc and Akt only, in GFAP-expressing cells, led to only one tumor in 27 mice." (PMID 23424671, 2013). "The cells transfected with the hNIS gene under the control of the tumor-specific GFAP promoter, took in radioiodine and had lower survival rates for 131I-treated U251 and U87 cells compared with the control cells (transfected with Ad-CMV-EGFP) in vitro." (PMID 23420532, 2013). "The presence of human EC-like cells in GSLC-derived tumors was confirmed by co-staining of tumor tissues in which a proportion of CD31+ cells also expressed the glial marker GFAP (top), consistent with the findings in primary human GBM." (PMID 23536763, 2013). "The tumor cells were cuboidal to columnar in shape with strong immunostaining for glial fibrillary acidic protein and S-100." (PMID 24137352, 2013). "Here, GFAP showed decreased expression in LX-2 after tumor stimulation, which can partly interpret its transform from an activated marker in chronic liver disease to negative expression in HCC tissues." (PMID 23601182, 2013). "Upon irr, the majority of GBM cells lost their Nestin expression, whereas a large fraction of GBM cells near central tumor mass strongly upregulated the astrocytic differentiation marker GFAP." (PMID 24052948, 2013). "Tumour incidence and volume, plus immunoreactivity to albumin, IBA1 and GFAP, were used as indicators of tumorigenicity and tumour interaction with the host brain microenvironment." (PMID 23374226, 2013). "Correspondingly, there was a significant increase in the number of astrocytes immunostained for GFAP in the striatum surrounding the tumour mass 7 days following direct injection of CRCTU Walker 256 cells (p<0.01)." (PMID 23374226, 2013). "GBM cells can respond to differentiation cues and alter patterns of gene expression – for example, response to BMP suppresses tumour initiation and is accompanied by the upregulation of GFAP." (PMID 22771539, 2013). "In the secondary section of the tumor, only the oligodendrocyte-like cells were positive for Oligo-2, while the astrocytes and the oligodendrocyte-like cells were positive for GFAP." (PMID 24137435, 2013). "Tumor promoters, such as the glial fibrillary acidic protein (GFAP) and human telomerase reverse transcriptase (hTERT) promoters, limit the expression of the hNIS gene in specific cells, achieving the selective expression of targeted radioiodine therapy." (PMID 23420532, 2013). "Immunohistochemistry shows patchy expression of GFAP and S100b protein in tumour cells, a feature seen in a some MG patients." (PMID 23762429, 2013). "In the tumor border zone, where mouse nestin-positive cells accumulated, elongated bipolar cells expressed both nestin and GFAP." (PMID 22539956, 2012). "The lesion consisted of elongated and plump tumor cells that were arranged in a fascicular or storiform pattern and were positive for S-100 protein and focally positive for glial fibrillary acidic protein." (PMID 22989192, 2012).
tumor (continued). "We then used GFP immunofluorescence to identify tumor progeny cells and stained the same tissue for GFAP to identify astrocytes and look for co-localization." (PMID 22393407, 2012). "We then compared adjacent tissue sections from tumor-bearing mouse brains stained for mouse nestin or GFAP." (PMID 22539956, 2012). "Rat nestin and GFAP double-positive cells were more numerous in the tumor periphery, but were also found in the tumor core." (PMID 22539956, 2012). "TAAs surrounding the tumor are morphologically ‘reactive’ with swollen cell bodies, hyperextended processes extending in multiple directions, and they express high levels of GFAP." (PMID 22393407, 2012). "It is worth noting that a large percentage of PDGF-RFP infected cells expressed low levels of GFP and, given our staining and FACS data, these represent PDGF-infected Olig2+ tumor cells that also express low levels of GFAP." (PMID 22393407, 2012). "In the tumor, cells with elongated morphology, as well as cells with astrocytic morphology stained positively for both rat nestin and GFAP." (PMID 22539956, 2012). "Immunohistology showed that these tumor masses presented a more mature morphology than that in control groups, characterized by the increased expression of GFAP, and less ventricular invasion." (PMID 22650359, 2012). "Finger like projections are lined by single or multiple layers of cuboidal tumor cells with smooth contiguous surfaces and with GFAP-positive tumor cell processes." (PMID 22472343, 2012). "Analysis of the serial imaging supports a model in which intracranial tumor injection induces an early GFAP response, which is likely a consequence of the local wounding of the stereotactic injection." (PMID 21247490, 2011). "GFAP promoter activation was used as a surrogate marker for host compartment astrogliosis to assess tumor progression." (PMID 21247490, 2011). "Together, these results indicate that GFAP activity can be used as a surrogate marker for tumor-induced astrogliosis." (PMID 21247490, 2011). "Here we show that these GFAP-luc; Rag2-/- mice injected with malignant glioma cells can be used to monitor and quantify tumor-induced astrogliosis response of the host." (PMID 21247490, 2011). "Using transgenic mice expressing firefly luciferase under the regulation of the GFAP promoter (GFAP-luc), we developed a model system to monitor astrogliosis upon tumor growth in a rapid, non-invasive manner." (PMID 21247490, 2011). "On day 18, the rats were sacrificed and the antitumour effect was determined by measurement of tumour size, necrotic areas, proliferation index, and expression of GFAP and VEGF as well as Isolectin B4, a marker for the vessel density." (PMID 21573151, 2011). "The pattern of differentiation in the tumor cell layers around the angiogenic vessel, is examined for neuronal markers GFAP, NFP and Syn." (PMID 21080952, 2010). "Concentric layers of tumor cells grow out from this layer, supported by GFAP positive processes which extend outward through the layers of tumor cells towards the periphery." (PMID 21080952, 2010). "For instance, transfection of P21WAF1/CIP1 gene can enhance the GFAP expression, thus enabling the tumor cells to achieve terminal differentiation." (PMID 20716331, 2010). "The expression of neural markers [GFAP, NFP and Syn], by melanocytes in association with pigmentation and the tumor morphology has been examined in this section." (PMID 21080952, 2010). "Glial fibrillary acidic protein (GFAP) was immunohistochemically localized in order to determine the tumour area by image analysis." (PMID 19292920, 2009). "Intense immunohistochemical positivity to glial fibrillary acidic protein (GFAP) confirmed the astrocytic phenotype of the tumor." (PMID 17587463, 2007). "Additional evaluation of tumor cells for glial fibrillary acidic protein (GFAP) immunoreactivity with clinical details resulted in final interpretation of metastatic GBM." (PMID 15967023, 2005).